ACOT8 (acyl-CoA thioesterase 8)
Description:
Catalyzes the hydrolysis of acyl-CoAs into free fatty acids and coenzyme A (CoASH), regulating their respective intracellular levels. Displays no strong substrate specificity with respect to the carboxylic acid moiety of Acyl-CoAs (By similarity). Hydrolyzes medium length (C2 to C20) straight-chain, saturated and unsaturated acyl-CoAS but is inactive towards substrates with longer aliphatic chains. Moreover, it catalyzes the hydrolysis of CoA esters of bile acids, such as choloyl-CoA and chenodeoxycholoyl-CoA and competes with bile acid CoA:amino acid N-acyltransferase (BAAT) (By similarity). Is also able to hydrolyze CoA esters of dicarboxylic acids (By similarity). It is involved in the metabolic regulation of peroxisome proliferation. (Microbial infection) May mediate Nef-induced down-regulation of CD4 cell-surface expression.
Synonyms: PTE-2; PTE-1; hACTE-III; hTE; PTE1; NAP1; HNAACTE; PTE2
Tractability: PROTAC: ubiquitination databases record sites on it; its protein half-life has been measured.
Gene: Protein-coding gene on chromosome 20 (45,841,709 to 45,857,405, reverse strand). Ensembl gene ENSG00000101473.
Subcellular location: Peroxisome matrix
Subcellular location (Human Protein Atlas): Vesicles; Mitochondria
Pathways (Reactome):
Metabolism: Beta-oxidation of pristanoyl-CoA; Beta-oxidation of very long chain fatty acids; Synthesis of bile acids and bile salts via 7alpha-hydroxycholesterol; alpha-linolenic acid (ALA) metabolism
Protein localization: Peroxisomal protein import
Gene Ontology:
Molecular function: acetyl-CoA hydrolase activity; fatty acyl-CoA hydrolase activity; long-chain fatty acyl-CoA hydrolase activity; medium-chain fatty acyl-CoA hydrolase activity; protein binding; acetoacetyl-CoA hydrolase activity; acyl-CoA hydrolase activity; choloyl-CoA hydrolase activity; hydroxymethylglutaryl-CoA hydrolase activity; succinyl-CoA hydrolase activity; short-chain fatty acyl-CoA hydrolase activity
Biological process: acyl-CoA metabolic process; dicarboxylic acid catabolic process; negative regulation of glycoprotein biosynthetic process; peroxisome fission; alpha-linolenic acid metabolic process; bile acid biosynthetic process; fatty acid beta-oxidation using acyl-CoA oxidase; fatty acid catabolic process; fatty acid biosynthetic process; fatty acid metabolic process
Cellular component: peroxisomal matrix; cytosol; peroxisome
Genetic constraint (gnomAD): Loss-of-function variants: 33 observed, 40.25 expected, observed/expected ratio (o/e) 0.82, 90% interval 0.62 to 1.1. The upper end of that interval is the gene's LOEUF score, 1.1, which puts it in group 4 of 6, group 1 being the genes least tolerant of losing a copy. Missense variants: 373 observed, 436.35 expected, observed/expected ratio (o/e) 0.85, 90% interval 0.79 to 0.93. Synonymous variants: 158 observed, 177.24 expected, observed/expected ratio (o/e) 0.89, 90% interval 0.78 to 1.02.
Homologues: Orthologues: chimpanzee ACOT8 (99% identical), macaque ACOT8 (98% identical), dog ACOT8 (88% identical), pig ACOT8 (87% identical), rat Acot8 (86% identical), guinea pig ACOT8 (85% identical), mouse Acot8 (85% identical), rabbit ACOT8 (82% identical), tropical clawed frog acot8 (71% identical), zebrafish acot8 (66% identical), Caenorhabditis elegans F25E2.3 (39% identical), Caenorhabditis elegans C37H5.13 (39% identical), and 3 more.
Diseases named in the same sentence as ACOT8 in open-access papers:
ACOT8 is named in the same sentence as 20 diseases in open-access papers, as found by Europe PMC text mining. Sharing a sentence is not in itself a finding about the gene and the disease. The quoted sentences say what the papers report.
hepatocellular carcinoma (4 papers, 2019 to 2022). A malignant tumor that arises from hepatocytes. "The expression level of ACOT8 was significantly upregulated in clinical samples of hepatocellular carcinoma (HCC), resulting in lower cumulative survival." (PMID 36193167, 2022). "It has been reported that ACOT8 participates in multiple cancer tumorigeneses, such as hepatocellular carcinoma, colorectal cancer, and lung adenocarcinoma." (PMID 34922551, 2021). "The potential role of ACOT8 in cancer development has been raised regarding the reports of its overexpression in hepatocellular carcinoma and ovarian cancer cells." (PMID 32155177, 2020). "Similar to this finding, the expression of ACOT8 was increased in hepatocellular carcinoma and lung adenocarcinoma, indicating it might serve as a potential prognostic biomarker of these cancers." (PMID 34922551, 2021).
lung adenocarcinoma (4 papers, 2020 to 2025). A carcinoma that arises from the lung and is characterized by the presence of malignant glandular epithelial cells. "High expression of ACOT1 is related to unfavorable prognosis of gastric adenocarcinoma via increased tumor-promoting protein GLI3, while ACOT8 is demonstrated to be an independent predictor of lymph node metastasis and survival of lung adenocarcinoma." (PMID 33362855, 2020). "Meanwhile, the possible prognostic role of ACOT8 has only investigated during lymph node metastasis of lung adenocarcinoma in which the authors reported that ACOT8 upregulation was associated with poorer prognosis of lung cancer patients." (PMID 32155177, 2020). "For instance: ACOT8 overexpression correlates with lung adenocarcinoma metastasis and may mediate intracellular lipid metabolism." (PMID 40978035, 2025).
clear cell renal cell carcinoma (1 paper, 2023). "In clear cell renal cell carcinoma (ccRCC), the majority of ACOT members, including ACOT1, ACOT2, ACOT3, ACOT8 and ACOT11, are downregulated in the cancer samples." (PMID 37003979, 2023).
diabetes (1 paper, 2023). "Considering that in diabetes and after prolonged starvation mobilized lipid is mainly transported in the form of plasma albumin-bound fatty acids, rather than TG, these results suggest that ACOT12 and ACOT8 might be required for rapid degradation of fatty acids in these cases." (PMID 37902629, 2023).
fatty liver (1 paper, 2024). "Similar to our findings, Zengpeng and colleagues demonstrated that dietary genistein supplementation resulted in the upregulation of gene transcription associated with fatty acid beta-oxidation, including PPARα, PPARδ, ACOT8, ACAD8, and ACADs in the liver of laying hens induced fatty liver." (PMID 38540097, 2024).
HIV-1 infection (1 paper, 2016). The type species of lentivirus and the etiologic agent of acquired immunodeficiency syndrome (AIDS). "The study also showed that the Nef membrane localization is not strictly required for the interaction with ACOT8, suggesting that their association might occur early during HIV-1 infection." (PMID 26927806, 2016).
pancreatic cancer (1 paper, 2025). "However, the regulatory role of ACOT8 in the metabolic state of pancreatic cancer cells and the mechanism of ferroptosis under other common stress conditions (such as hypoxia) remain to be explored." (PMID 39939803, 2025).
cancer (5 papers, 2020 to 2025). A tumor composed of atypical neoplastic, often pleomorphic cells that invade other tissues. "Overall, ACOT8 can significantly promote the function of cancer cells; accordingly, reducing ACOT8 expression can effectively inhibit growth both in vivo and in vitro." (PMID 39939803, 2025). "We observed that ACOT8 expression levels were positively correlated with the proliferation and migration ability of cancer cells." (PMID 39939803, 2025). "Overall, these findings suggest a significant correlation of ACOT8 expression with cancer grade, drug resistance, and patient prognosis; moreover, they demonstrate the potential diagnostic and therapeutic utility of ACOT8." (PMID 39939803, 2025). "The predicted estimation of being diagnosed with cancer from the log it model based on the five selected lipogenic genes panel, and Log it (P) = 0.429 + 0.659 x ACOT8 + 0.084 x ACSL5 + 0.029 x FASN + 0.201 x HMGCS2 + 0.119 x SCD1 was used to create the ROC curve." (PMID 32155177, 2020). "Additionally, ACOX3, ACAD9, ACAD10, ACOT1, ACOT8, and DECR2 displayed positive associations with PEBP1/STK11 co-expression across various cancer types, highlighting a potential involvement in enhancing fatty acid metabolism in the context of PEBP1/STK11 expression." (PMID 40806276, 2025). "Our study highlights the impact of ACOT8, ACSL5, FASN, HMGBCS2, and SCD1 genes in lipid metabolism along with their distinctive role in cancer initiation and progression." (PMID 32155177, 2020).
tumor (4 papers, 2020 to 2025). "Taken together, these results demonstrate that the transcriptional expression of ACOT8 is significantly associated with tumor progression in ccRCC patients." (PMID 33362855, 2020). "Analysis of the staining scores and patient data revealed that ACOT8 expression was significantly higher in the tumor group (T) than in the paracancer group (TP)." (PMID 39939803, 2025). "Orlistat, which is a lipid-lowering and weight-loss drug widely used in clinical practice, inhibits the expression of ACOT8 and induces tumor cell ferroptosis." (PMID 39939803, 2025). "Intriguingly, although ACOT8 was significantly decreased in ccRCC tissues compared with that in normal kidney tissues, its transcriptional expression level kept rising as the tumor progressed." (PMID 33362855, 2020). "Additionally, the grade of tumor differentiation was correlated with the ACOT8 expression level, and the staining scores were significantly increased in the low differentiation group." (PMID 39939803, 2025). "Additionally, the subcutaneous tumorigenic model revealed a significantly greater tumor diameter in the ACOT8-overexpression group." (PMID 39939803, 2025). "Mechanistically, a large number of biomolecules and tumor-associated signaling pathways, including DECR1, PANX2, HSPB1, ACOT8, SUV39H1, NCOA4, PI3K-AKT-mTOR signaling, VHL/HIF-2α pathway, and Hippo/TAZ signaling pathway, have been reported to regulate ferroptosis in urologic cancers." (PMID 34922551, 2021). "Similarly, there was no significant relation between ACOT1/2/11/13 and histological grades, while the mRNA level of ACOT8 increased with tumor grades." (PMID 33362855, 2020). "Given that higher ACOT8 represents shorter overall survival of ccRCC as concluded above, we postulated that ACOT8 might take part in ferroptosis inhibition to regulate tumor progression." (PMID 33362855, 2020). "Our study showed that the panel of ACOT8/ACSL5/FASN/HMGBCS2/SCD1 genes had a better prognostic performance than validated clinical risk scales and is applicable for early detection of CRC and tumor recurrence." (PMID 32155177, 2020). "Furthermore, ACOT8 was found to promote tumor development in lung and liver cancers." (PMID 39939803, 2025). "The combination of orlistat, an ACOT8 inhibitor, and GEM significantly inhibited tumor growth in PDAC organoid and mouse models." (PMID 39939803, 2025). "To further investigate the functional characteristics of ACOT8 in ccRCC, we performed GSEA on 598 samples (72 normal vs 526 tumor) from TCGA database." (PMID 33362855, 2020).
ACOT8 also shares sentences with these, for which no sentence is quoted: infection (2 papers); lymph node metastasis (2); Anxiety (1); asthma (1); gastric adenocarcinoma (1); lung carcinoma (1); melanoma (1); nutritional deficiency (1); ovarian carcinoma (1); pancreatic ductal adenocarcinoma (1); prostate adenocarcinoma (1).